NLGN2 (neuroligin 2)
Description:
Transmembrane scaffolding protein involved in cell-cell interactions via its interactions with neurexin family members. Mediates cell-cell interactions both in neurons and in other types of cells, such as Langerhans beta cells. Plays a role in synapse function and synaptic signal transmission, especially via gamma-aminobutyric acid receptors (GABA(A) receptors). Functions by recruiting and clustering synaptic proteins. Promotes clustering of postsynaptic GABRG2 and GPHN. Promotes clustering of postsynaptic LHFPL4 (By similarity). Modulates signaling by inhibitory synapses, and thereby plays a role in controlling the ratio of signaling by excitatory and inhibitory synapses and information processing. Required for normal signal amplitude from inhibitory synapses, but is not essential for normal signal frequency. May promote the initial formation of synapses, but is not essential for this. In vitro, triggers the de novo formation of presynaptic structures. Mediates cell-cell interactions between Langerhans beta cells and modulates insulin secretion (By similarity).
Synonyms: KIAA1366
Tractability: Small molecule: it belongs to a druggable protein family. Antibody: its Gene Ontology location is reachable by antibodies, with high confidence; UniProt places it where antibodies can reach, with medium confidence; UniProt predicts a signal peptide or a membrane-spanning region. PROTAC: ubiquitination databases record sites on it; its protein half-life has been measured.
Gene: Protein-coding gene on chromosome 17 (7,404,874 to 7,419,860, forward strand). Ensembl gene ENSG00000169992.
Subcellular location: Cell membrane; Postsynaptic cell membrane; Presynaptic cell membrane; Cell projection, dendritic spine; Cell projection, dendrite; Synapse
Subcellular location (Human Protein Atlas): Mitochondria
Pathways (Reactome):
Neuronal System: Neurexins and neuroligins
Gene Ontology:
Molecular function: protein binding; cell adhesion molecule binding; neurexin family protein binding; cell adhesion mediator activity; identical protein binding
Biological process: positive regulation of insulin secretion; positive regulation of protein localization to synapse; cell-cell adhesion; cell-cell junction maintenance; gephyrin clustering involved in postsynaptic density assembly; modulation of chemical synaptic transmission; neuron cell-cell adhesion; positive regulation of excitatory postsynaptic potential; positive regulation of inhibitory postsynaptic potential; positive regulation of synapse assembly; positive regulation of synaptic transmission, GABAergic; positive regulation of synaptic transmission, glutamatergic; postsynaptic density protein 95 clustering; postsynaptic membrane assembly; presynapse assembly; presynaptic membrane assembly; protein localization to synapse; regulation of respiratory gaseous exchange by nervous system process; synapse assembly; synapse organization; terminal button organization; inhibitory synapse assembly; insulin metabolic process; jump response; locomotory exploration behavior; and 10 more
Cellular component: plasma membrane; cell surface; inhibitory synapse; membrane; postsynaptic membrane; postsynaptic specialization membrane; presynaptic membrane; symmetric, GABA-ergic, inhibitory synapse; synapse; axon; dendrite; dendritic shaft; dendritic spine; dopaminergic synapse; excitatory synapse; GABA-ergic synapse; glycinergic synapse; neuron to neuron synapse; ribbon synapse
Genetic constraint (gnomAD): Loss-of-function variants: 12 observed, 48.48 expected, observed/expected ratio (o/e) 0.25, 90% interval 0.16 to 0.4. The upper end of that interval is the gene's LOEUF score, 0.4, which puts it in group 1 of 6, group 1 being the genes least tolerant of losing a copy. Missense variants: 738 observed, 1,073.2 expected, observed/expected ratio (o/e) 0.69, 90% interval 0.65 to 0.73. Synonymous variants: 516 observed, 475.04 expected, observed/expected ratio (o/e) 1.09, 90% interval 1.01 to 1.17.
Homologues: Orthologues: macaque NLGN2 (100% identical), chimpanzee NLGN2 (99% identical), dog NLGN2 (99% identical), rat Nlgn2 (98% identical), mouse Nlgn2 (98% identical), rabbit NLGN2 (98% identical), guinea pig NLGN2 (77% identical), tropical clawed frog nlgn2 (75% identical), zebrafish nlgn2a (74% identical), Drosophila melanogaster CG4382 (19% identical), Drosophila melanogaster Glt (19% identical), Drosophila melanogaster CG3841 (19% identical), and 39 more. Paralogues in human: NLGN3 (63% identical), NLGN1 (63% identical), NLGN4X (62% identical), NLGN4Y (62% identical), CES5A (24% identical), CES2 (24% identical), CES3 (23% identical), CES1 (23% identical), CES4A (23% identical), ACHE (22% identical), BCHE (22% identical), TG (21% identical), and 1 more.
Diseases named in the same sentence as NLGN2 in open-access papers:
NLGN2 is named in the same sentence as 41 diseases in open-access papers, as found by Europe PMC text mining. Sharing a sentence is not in itself a finding about the gene and the disease. The quoted sentences say what the papers report.
Anxiety (21 papers, 2013 to 2025). Intense feelings of nervousness, tension, or panic often arise in response to interpersonal stresses. "Altered expression and mutations in NLGN2 and several of its interacting partners are linked to cognitive and psychiatric disorders, including schizophrenia, autism, and anxiety." (PMID 35963640, 2022). "On the receptor side, a nonsense variant in NLGN2 was reported in a patient with severe anxiety, obsessive-compulsive behaviors, autism, short attention span, global develop-mental delays, hyperphagia, obesity, macrocephaly, and dysmorphic features." (PMID 35501678, 2022). "In their study, they found a marked increase in anxiety-like behavior, a decrease in pain sensitivity, and a slight decrease in motor coordination in the Nlgn2-deficient mice." (PMID 29230184, 2017). "The loss of function of Nlgn2 in mice leads to relative selective increase in behavioral anxiety." (PMID 30998708, 2019). "Deletion of IgSF9b increased the number of VIAAT puncta in Nlgn2 KO mice (red and blue striped bars), an effect that may underlie the rescue of anxiety-related behavior in Nlgn2 KO mice following local deletion of IgSF9b in the CeM." (PMID 30573727, 2018). "However, we noticed that Nlgn2 KO mice displayed frequent stretch-attend postures (SAPs), a risk-assessment behavior that reflects an internal conflict between anxiety and the exploratory drive." (PMID 30573727, 2018). "At present, both the function of these beta oscillations in anxiety processing and the mechanisms that underlie their modulation by Nlgn2 and IgSF9b remain unknown." (PMID 30573727, 2018). "In addition, a nonsense mutation of NLGN2 was detected recently in a young male patient manifesting severe anxiety, obsessive-compulsive behaviors, autism, intellectual disability, and other aberrant developmental features." (PMID 29230184, 2017). "The strong correlation of power of beta oscillations with distance from the center of the OF in Nlgn2 KO mice and its exacerbated increase during risk-assessment behavior implicates beta oscillations in the CeM as a key neural signature of pathological anxiety." (PMID 30573727, 2018). "The normalization of the cytoplasmic gephyrin aggregates correlates well with the partial normalization of sIPSC frequency and amplitude, as well as with the partial normalization of the anxiety behavior in the female Nlgn2/MDGA1 dKO mice." (PMID 39284869, 2024). "Like Nlgn2+/– animals, Rorb-mutant mice showed normal anxiety-like and social behaviors compared to control littermates." (PMID 38233682, 2024). "In humans, mutations in NLGN2 have been linked to ASD and schizophrenia, while rodents with NLGN2 deregulations have been found to have behavioral impairments, such as anxiety-like behaviors and impaired social interactions." (PMID 38570872, 2024). "Abnormal expression of NLGN2 will lead to anxiety, growth retardation, dyskinesia, social disorders, aggressive and sensory processing defects, and changes in social skills in animal models." (PMID 37786892, 2022). "Nlgn2 has been implicated in negative social processing and aggressive behavior, with several publications showing a link between altered Nlgn2 expression and aggression-related behaviors, anxiety, and altered social behaviors." (PMID 35601025, 2022). "A recent study demonstrated a link among γ-protocadherins, Nlgn2 expression, and social and anxiety-like behaviors, suggesting γ-protocadherin as possible negative regulators of Nlgn2-driven inhibitory synapse formation and function." (PMID 35601025, 2022). "Studies on NLGN2 gene knockout mice showed that NLGN2 has unique functions in maintaining inhibitory synaptic function and regulating anxiety behavior." (PMID 37786892, 2022). "Overexpression of Nlgn2 in transgenic mice had displayed diverse behavioural deficits such as reduced lifespan, limb clasping, offspring viability, repetitive behaviour, anxiety and impaired social interactions." (PMID 31185809, 2019).
Anxiety (continued). "Nlgn2 KO mice showed reduced anxiety, increased impulsivity in the elevated plus maze and reduced fear conditioning with an increased ratio of evoked E/I synaptic currents." (PMID 31185809, 2019). "Combined evidence from our cFos analysis, retrograde tracing experiments, and in vivo electrophysiology indicates that IgSF9b deletion normalizes anxiety-related output specifically in the CeM of Nlgn2 x IgSF9b double KO mice." (PMID 30573727, 2018). "Second, do IgSF9b and/or Nlgn2 act at specific inhibitory synapses within the anxiety circuitry and thus offer synapse-specific targets for interventions?" (PMID 30573727, 2018). "Further experiments will be essential to fully understand how Nlgn2 and IgSF9b regulate beta oscillations in the CeM and how this contributes to the generation and normalization of pathological anxiety processing." (PMID 30573727, 2018). "In the present study we sought to elucidate the role of the cell adhesion molecule IgSF9b and its interactions with Nlgn2 in amygdala circuits, synapses, and behaviors related to anxiety processing." (PMID 30573727, 2018). "The increase in the beta frequency band was most prominent in Nlgn2 KO mice, indicating that Nlgn2 deletion modifies anxiety-related CeM activity in the beta frequency range." (PMID 30573727, 2018). "Most strikingly, the prominent anxiety phenotype of the single Nlgn2 KO mice was completely abolished in the double KO mice, with all measures unchanged from WT levels (purple bars)." (PMID 30573727, 2018). "We show that deletion of IgSF9b has anxiolytic consequences and normalizes the prominent anxiety phenotype observed in Nlgn2 KO mice." (PMID 30573727, 2018). "We show that IgSF9b regulates anxiety-like behaviors in Nlgn2 KO mice and that IgSF9b and Nlgn2 exert differential effects on distinct components of the amygdala inhibitory circuitry." (PMID 30573727, 2018). "Given that the normalization of anxiety-related behaviors can be mimicked by local shRNA-mediated knockdown of IgSF9b in the CeM of Nlgn2 KO mice, it is likely to occur through a local mechanism within the CeM." (PMID 30573727, 2018). "Taken together, these findings indicate that dysfunction of NLGN2 contributes to the genesis of anxiety-like behaviors." (PMID 29230184, 2017). "The transgenic animals were viable and fertile, but the Nlgn2 R215H knock-in (KI) homozygous mice showed growth retardation, anxiety-like behavior, increased PPI, and impaired spatial learning and memory." (PMID 29230184, 2017). "The anxiety-like behaviors are also in line with the findings in the Nlgn2 knockout mice reported by Blundell and colleagues." (PMID 29230184, 2017). "In their study, they conducted conditional knockout of Nlgn2 in the medial prefrontal cortex of adult mice and found that the conditional knockout mice showed less anxiety-like behavior, which is opposite to our finding in our animals." (PMID 29230184, 2017). "Since Nrxn1α binds to neuroligin 2, we investigated anxiety-like behaviour by using the open field, light/dark box, and the elevated plus maze." (PMID 23840597, 2013). "Given this correlation, it is conceivable that the formation of these gephyrin aggregates contributes to the anxiety phenotype in the Nlgn2 KO mice, and that reversing gephyrin aggregate formation may ameliorate this behavior." (PMID 39284869, 2024). "We show that combined deletion of Nlgn2 and MDGA1 results in a partial reversal of the prominent anxiety phenotype observed in female Nlgn2 KO mice, consistent with the normalization of gephyrin aggregates and the partial normalization of sIPSC frequency in CA1 pyramidal neurons." (PMID 39284869, 2024). "In keeping with our observations in adult global Nlgn2-mutant animals, neither sensory nor spinal cord neuron loss of Nlgn2 expression affected anxiety-like or social behaviors, despite tactile overreactivity in the spinal cord Nlgn2 mutants." (PMID 38233682, 2024).
Anxiety (continued). "We show that loss of MDGA1 expression, but not heterozygous deletion of MDGA2, ameliorates the abnormal cytosolic gephyrin aggregation, the reduction in inhibitory synaptic transmission and the exacerbated anxiety-related behaviour characterizing Nlgn2 knockout (KO) mice." (PMID 39284869, 2024). "In the present study, we used an open field task to test whether this anxiety phenotype is modulated in Nlgn2/MDGA1 dKO or Nlgn2 KO/MDGA2 Het mice." (PMID 39284869, 2024). "Accordingly, we were unable to determine whether the anxiety phenotype of Nlgn2 KO mice is also ameliorated in male Nlgn2/MDGA1 dKO mice." (PMID 39284869, 2024). "Conditional knockout of Nlgn2 in the medial prefrontal cortex of adult mice exhibited chronic changes in synaptic inhibition and cognitive impairments, including decreased anxiety-related response, contextual and cued fear conditioning, and social interactions." (PMID 35664469, 2022). "In the present study, we investigated the role of synaptic inhibition in anxiety by addressing two key questions: First, does IgSF9b regulate anxiety-related behavior and neural processing in the anxiety circuitry of WT and/or pathologically anxious Nlgn2 KO mice?" (PMID 30573727, 2018). "To address the role of IgSF9b in anxiety processing, we first tested whether IgSF9b deletion would alter anxiety-related behaviors and/or modulate the anxiety phenotype observed in Nlgn2 KO mice." (PMID 30573727, 2018). "Furthermore, Babaev and colleagues also reported that Nlgn2 knockout mice showed a robust anxiety phenotype in all three anxiety tests, including the EPM, the open field test, and the light/dark exploration test." (PMID 29230184, 2017). "However, global overexpression of NLGN2 resulted in an enhancement of anxiety-like behavior despite the observed potentiated GABAergic function." (PMID 24039767, 2013). "In NLGN2-overexpressing mice, high levels of basal activity, enhanced startle response, anxiety and stereotyped jumping behavior was observed that may be the result of an increased level of arousal." (PMID 24039767, 2013). "Interestingly, despite the opposite changes in the strength of GABAergic transmission detected in NLGN2-KO and NLGN2-overexpressing mice, both mice showed increased anxiety-like behavior." (PMID 24039767, 2013). "Indeed, Nlgn2 and Rorb heterozygous mutant animals exhibit normal anxiety-like and social behaviors in adulthood, although it is possible that these animals may exhibit ASD-associated behavioral alterations not examined here or in prior studies." (PMID 38233682, 2024). "Therefore, we tested generalization in Neuroligin 2 knockout (KO) mice, as a model of anxiety." (PMID 30998708, 2019). "To this end, we investigated the consequences of IgSF9b deletion and IgSF9b x Nlgn2 double deletion on anxiety-related behavior and circuits, as well as on inhibitory synapses in the amygdala, a brain region that plays a central role in the processing of anxiety information." (PMID 30573727, 2018). "Together, these data indicate that Nlgn2 and IgSF9b deletion affect distinct targets within the amygdala: While Nlgn2 regulates anxiety-induced activation of projection neurons in BA, IgSF9b may normalize the CeM anxiogenic output by local mechanism within the CeM." (PMID 30573727, 2018). "boundary was observed in Nlgn2/MDGA1 dKO mice, accompanied by a partial normalization of defects in sIPSC characteristics in CA1 pyramidal neurons and of the anxiety-related behavior in an open field test." (PMID 39284869, 2024). "Surprisingly, however, male Nlgn2 KO mice in this experiment did not display the anxiety phenotype previously observed, likely due to complex interactions with strain background or parental behavior of the Nlgn2 Het/MDGA1 Het breeders." (PMID 39284869, 2024).
Anxiety (continued). "No amelioration of the Nlgn2 KO anxiety phenotype was observed in male or female Nlgn2 KO/MDGA2 Het mice, consistent with the lack of an effect of MDGA2 Het on gephyrin aggregation and GABAergic synaptic transmission." (PMID 39284869, 2024). "We show that deletion of IgSF9b normalizes anxiety-related behaviors and neural processing in mice lacking the synapse organizer Neuroligin-2 (Nlgn2), which was proposed to complex with IgSF9b." (PMID 30573727, 2018). "While it was originally proposed that IgSF9b links to Nlgn2 via S-SCAM as a bridging molecule and thereby recruits gephyrin and other GABAergic synapse components, we subsequently found that, at least within the amygdala anxiety circuitry, IgSF9b and Nlgn2 do not appear to act at the same synapses." (PMID 41105221, 2025). "Despite these marked changes in tactile reactivity and texture discrimination, Nlgn2+/– mice showed no alterations in anxiety-like or social interaction behaviors compared to control littermates, although Nlgn2–/– mice exhibited reduced time spent in the center of the open field." (PMID 38233682, 2024). "Interestingly, anxiety levels appeared to be exacerbated in Nlgn2 KO but not in WT mice over the observed 6-week time period, even in mice that had not undergone surgery, and this effect was completely reversed by local reduction of IgSF9b." (PMID 30573727, 2018). "Given that IgSF9b and Nlgn2 function at distinct synapses and do not appear to interact in a cell-autonomous manner, at least in the amygdala, how does deletion of IgSF9b normalize the prominent anxiety phenotype observed in Nlgn2 KO mice?" (PMID 30573727, 2018). "By contrast, and consistent with the hypothesis that normal tactile reactivity during development may be predictive of normal anxiety-like and social behaviors in adulthood, the reactivity of Nlgn2- and Rorb-mutant animals to air puffs was indistinguishable from that of control littermates at P4." (PMID 38233682, 2024). "However, no shift was observed in the Nlgn2 knockout mice, a model of anxiety." (PMID 30998708, 2019). "Taken together, our observations indicate functional interactions between MDGA1 and Nlgn2 KOs, but not between MDGA2 and Nlgn2 KOs, in modulating the neuronal circuits that regulate anxiety-related avoidance behaviors." (PMID 39284869, 2024).